SCT (secretin)
Description:
Hormone involved in different processes, such as regulation of the pH of the duodenal content, food intake and water homeostasis. Exerts its biological effects by binding to secretin receptor (SCTR), a G protein-coupled receptor expressed in the basolateral domain of several cells. Acts as a key gastrointestinal hormone by regulating the pH of the duodenal content (By similarity). Secreted by S cells of the duodenum in the crypts of Lieberkuehn and regulates the pH of the duodenum by (1) inhibiting the secretion of gastric acid from the parietal cells of the stomach and (2) stimulating the production of bicarbonate (NaHCO(3)) from the ductal cells of the pancreas (By similarity). Production of bicarbonate is essential to neutralize the pH and ensure no damage is done to the small intestine by the gastric acid (By similarity). In addition to regulating the pH of the duodenal content, plays a central role in diet induced thermogenesis: acts as a non-sympathetic brown fat (BAT) activator mediating prandial thermogenesis, which consequentially induces satiation (Probable). Mechanistically, secretin released by the gut after a meal binds to secretin receptor (SCTR) in brown adipocytes, activating brown fat thermogenesis by stimulating lipolysis, which is sensed in the brain and promotes satiation (By similarity). Also able to stimulate lipolysis in white adipocytes (By similarity). Also plays an important role in cellular osmoregulation: released into the systemic circulation in response to hyperosmolality and acts at different levels in the hypothalamus, pituitary and kidney to regulate water homeostasis (By similarity). Also plays a role in the central nervous system, possibly by acting as a neuropeptide hormone: required for hippocampal synaptic function and neural progenitor cells maintenance (By similarity).
Tractability: Antibody: UniProt places it where antibodies can reach, with high confidence; its Gene Ontology location is reachable by antibodies, with high confidence; UniProt predicts a signal peptide or a membrane-spanning region.
Gene: Protein-coding gene on chromosome 11 (626,309 to 627,181, reverse strand). Ensembl gene ENSG00000070031.
Subcellular location: Secreted
Pathways (Reactome):
Signal Transduction: G alpha (s) signalling events; Glucagon-type ligand receptors
Gene Ontology:
Molecular function: G protein-coupled receptor binding; protein binding; digestive hormone activity; hormone activity; signaling receptor binding
Biological process: adenylate cyclase-activating G protein-coupled receptor signaling pathway; brain development; diet induced thermogenesis; hippocampus development; intracellular water homeostasis; negative regulation of gastrin-induced gastric acid secretion; pancreatic juice secretion; positive regulation of lipid catabolic process; positive regulation of pancreatic juice secretion; positive regulation of somatostatin secretion; regulation of appetite; regulation of synaptic plasticity; response to nutrient levels; embryonic digestive tract development; positive regulation of cAMP/PKA signal transduction
Cellular component: extracellular region
Genetic constraint (gnomAD): Loss-of-function variants: 17 observed, 7.94 expected, observed/expected ratio (o/e) 2.14. That is too few expected variants to judge how well the gene tolerates losing a copy. Missense variants: 182 observed, 114.33 expected, observed/expected ratio (o/e) 1.59, 90% interval 1.41 to 1.8. Synonymous variants: 76 observed, 45.15 expected, observed/expected ratio (o/e) 1.68, 90% interval 1.39 to 1.94.
Homologues: Orthologues: chimpanzee SCT (98% identical), macaque SCT (93% identical), pig SCT (72% identical), dog SCT (68% identical), mouse Sct (61% identical), rat Sct (61% identical).
Diseases named in the same sentence as SCT in open-access papers:
SCT is named in the same sentence as 77 diseases in open-access papers, as found by Europe PMC text mining. Sharing a sentence is not in itself a finding about the gene and the disease. The quoted sentences say what the papers report.
gastrinoma (11 papers, 2012 to 2025). "SASI is an angiographic test similar to ASVS used for insulinomas in which secretin is injected into the feeding vessels supplying the gastrinoma and gastrin levels are measured in the hepatic vein at 20, 40, 60, 90, and 120 s post injection." (PMID 38672582, 2024). "Serial measurement of gastrin levels following intravenous administration of secretin can also be performed revealing an increase in gastrin levels for patients with gastrinoma, whereas they decrease in healthy individuals." (PMID 29257854, 2017). "An increase of gastrin >120 pg/dL after 2–5 min of secretin infusion is considered a suggestive result for gastrinoma; the response to secretin is relative to the presence of receptors for secretin on the gastrinoma cells." (PMID 24213321, 2012). "It has been demonstrated that the secretin response is significantly related to the presence and density of secretin receptors in gastrinoma cells." (PMID 24213225, 2012). "However, in patients with gastrinomas, the gastrin levels paradoxically continue to rise or remain elevated after secretin administration, with levels more than 120 pg/mL being diagnostic of ZES." (PMID 38672582, 2024). "Fasting gastrin levels and secretin stimulation tests can be used in the diagnosis of gastrinomas." (PMID 36291833, 2022). "The diagnosis of gastrinoma can be confirmed with a secretin stimulation test, with an increase in circulating gastrin levels of >200 pg/ml above baseline after intravenous administration of 1–2 μg/kg of body weight of secretin." (PMID 25698559, 2015). "Intraoperative selective intra-arterial secretin stimulation and venous sampling of gastrin may be helpful in localising small sporadic gastrinomas." (PMID 24213225, 2012). "ZES was biochemically confirmed with a secretin stimulation test and dotatate positron emission tomography/computed tomography (PET/CT) revealed multiple areas of hyper-metabolic activity within the gastrinoma triangle." (PMID 35919366, 2022). "It is associated with increase in the number of G cells, poor response to secretin stimulation test, and absence of gastrinoma in the pancreas or duodenum." (PMID 25698559, 2015).
chronic pancreatitis (10 papers, 2014 to 2025). A chronic inflammatory process causing damage and fibrosis of the pancreatic parenchyma. "Diffusion weighted imaging, through the measurement of ADC values before and after secretin administration, has proven to be effective in differentiating healthy controls from patients with chronic pancreatitis, but shows weaknesses in grading patients in different stages of the disease." (PMID 37443666, 2023). "Secretin-enhanced MRCP allows for a quantitative assessment of exocrine pancreatic function by measuring the duodenal filling and provides a more accurate way to identify small-duct disease in mild chronic pancreatitis." (PMID 28207747, 2017). "In early chronic pancreatitis though, they may not be conclusive; and a direct pancreatic function test with secretin or endoscopic ultrasound (EUS) (for patients with suspected chronic pancreatitis but with CT or MRCP without a clear image) is needed." (PMID 39996177, 2025). "In patients with chronic pancreatitis, pancreatic ADC values may be useful in the diagnosis and assessment of the severity of the disease, while the ADC response to secretin administration has not been demonstrated to be useful." (PMID 37443666, 2023).
pancreatic cancer (8 papers, 1997 to 2023). "For example, the top mutated neuropeptide SCT (secretin) is amplified in 26 samples while deleted in five samples in pancreatic cancer." (PMID 28676692, 2017). "One possible hypothesis is that the increased secretin levels associated with antral H. pylori infection, either per se or by acting as a cocarcinogen, increase the risk of pancreatic cancer." (PMID 18986545, 2008). "Secretin-stimulated pancreatic juice (PJ), collected from the duodenum, presents a valuable biomarker source for the (earlier) detection of pancreatic cancer (PC)." (PMID 36982172, 2023). "Moreover, sampling of duodenal fluid after secretin stimulation represents a less invasive procedure for obtaining pancreatic juice than sampling directly from the pancreatic duct and would therefore be the method of choice when screening pancreatic cancer high-risk patients." (PMID 30611220, 2019). "Secretin stimulation has been proven to accelerate the development and frequency of pancreatic tumors induced by nitrosamines in a hamster model." (PMID 18986545, 2008). "In 5 of 12 pancreatic cancers, receptors for secretin were visualized, while binding for secretin was present in all tumour-free pancreata." (PMID 9166939, 1997). "Case-control study comparing bacterial and fungal (16S and 18S rRNA) profiles of secretin-stimulated duodenal fluid collections from 308 patients undergoing duodenal endoscopy including 134 normal pancreas control subjects, 98 patients with pancreatic cyst (s) and 74 patients with pancreatic cancer." (PMID 35663462, 2022). "Furthermore, secretin acts as a carcinogen of pancreatic cancer." (PMID 32784492, 2020).
autism (6 papers, 2005 to 2024). Persistent deficits in social interaction and communication and interaction as well as a markedly restricted repertoire of activity and interest as well as repetitive patterns of behavior. "Secretin: Secretin, a gastrointestinal (GI) hormone, has been extensively studied as a pharmacotherapeutic agent in the treatment of autism." (PMID 30911457, 2019). "Widespread interest has focused on secretin as a treatment for autism." (PMID 38397008, 2024). "Therefore, whether secretin holds a critical position in autism pathology and intervention remains enigmatic and needs to be further studied." (PMID 38397008, 2024). "To conclude, secretin is not an effective cure for autism, as the extensive media attention suggested at the very beginning." (PMID 16287506, 2005).
cystic fibrosis (6 papers, 2017 to 2024). Autosomal recessive disorder caused by pathogenic variants in the CFTR gene (cystic fibrosis transmembrane conductance regulator), which encodes a chloride and bicarbonate channel expressed in epithelial cells, and follow the diagnosis criteria. "CFTR is the same gene that is mutated in cystic fibrosis and is under the control of secretin." (PMID 38409681, 2024). "A prospective ePFT study in patients (>16 years) with cystic fibrosis and healthy normal subjects administered the secretin 25 min before the endoscope insertion and collected the pancreatic fluid between 30 and 45 min that significantly shorter than the 60 min test." (PMID 36452348, 2022). "The purpose of this study was to compare volume output measures from secretin-stimulated transabdominal ultrasonography (s-US) to s-MRI for the diagnosis of exocrine pancreatic failure in cystic fibrosis." (PMID 29134356, 2018). "The lack of HCO3- response to secretin is in complete agreement with the original studies in children with cystic fibrosis." (PMID 39170739, 2024).
liver fibrosis (6 papers, 2021 to 2023). "This activation of biliary proliferation effected by secretin is believed to initiate and progress hepatic fibrosis via a paracrine manner by activating hepatic stellate cells (HSCs) and autocrine profibrogenic factors." (PMID 35647306, 2022). "Recently, in animal models, cholangiocytes associated with the secretin (SCT)/secretin receptor (SCTR) axis have been linked to NAFLD pathogenesis, playing an important role in biliary injury and hepatic fibrosis." (PMID 34199535, 2021). "In rodents, inhibition of secretin/SR signaling or genetic knockout of secretin or SR decreases biliary hyperplasia and liver fibrosis in cholestatic models." (PMID 34440841, 2021). "These experimental data fully illustrate the role of secretin in the progression of liver fibrosis, and targeting the Sct/SR axis may provide a new therapeutic approach for liver fibrosis as well as bile duct disease." (PMID 36497043, 2022). "In addition, they found that secretin-stimulated TGF-β increased cholangiocytes senescence and decreased HSCs senescence via a paracrine pathway, further promoting liver fibrosis." (PMID 36497043, 2022). "Secretin-induced biliary secretion of TGF-β1 results in cholangiocyte senescence through an autocrine loop, which in turn increases the release of SASPs, including TGF-β1, and triggers hepatic fibrosis by decreasing HSC senescence." (PMID 35647306, 2022).
Obesity (6 papers, 2021 to 2025). Accumulation of substantial excess body fat. "Other GPCRs involved in neurohormonal signalling and associated with obesity and insulin resistance, such as OPRK1 and ADRB2, and receptors for peptide hormones, including somatostatin (SSTR1/2/5) and secretin (SCTR), were also enriched in K cells." (PMID 39441374, 2025). "The study advances our understanding of the secretin signaling in motivated eating behavior and highlights the potential role of secretin in treating eating disorders and obesity." (PMID 36764966, 2023). "Most importantly, our recent findings show that secretin both increases energy expenditure and reduces appetite, making it a potential anti-obesity agent." (PMID 34671320, 2021). "We have recently conducted an imaging study that further highlights the potential of secretin as an anti-obesity agent in humans." (PMID 34671320, 2021). "Moreover, the ventromedial hypothalamus-secretin inhibition also contributes to hyperphagia, dysregulated lipogenesis, and impaired thermogenesis, resulting in obesity in male and female mice." (PMID 38310104, 2024). "Both metabolic and cognitive level evidence suggests that secretin may be a potential drug for the treatment of eating disorders such as obesity." (PMID 36764966, 2023). "Collectively, secretin infusion or any that induces plasma secretin could be a competent therapeutic strategy to treat obesity and metabolic diseases." (PMID 35600577, 2022). "There is evidence that the increase of serum secretin in prolonged fasting is blunted in obesity." (PMID 34671320, 2021). "In this review, we discuss the evidence from preclinical and clinical studies based on which secretin may have a role in the treatment of obesity." (PMID 34671320, 2021). "Collectively, our findings identify an unappreciated secretin signaling in the central neural system for the regulation of energy and bone metabolism, which may serve as a new target for the clinical management of obesity and osteoporosis." (PMID 38310104, 2024). "Regarding the circulating markers of BAT activity, CXCL14, secretin, and 12,13-dihydroxy-9Z-octadecenoic acid (12,13 di-HOME) were similar in the two groups, whereas there was a trend for higher FGF21 in the subjects overweight/obesity." (PMID 35928901, 2022).
osteoporosis (6 papers, 2016 to 2024). A condition of reduced bone mass, with decreased cortical thickness and a decrease in the number and size of the trabeculae of cancellous bone (but normal chemical composition), resulting in increased fracture incidence. "We found specific osteoporosis-linked SNPs in genes encoding key receptors involved in bone metabolism that are classified into rhodopsin (ADRB2, CNR2, MTNR1B, FSHR, TSHR, LGR4), secretin (CALCR, GIPR), and other T7M (WLS) receptor families." (PMID 39769358, 2024). "Our previous clinical studies have found that QGY significantly improves BMD in patients with osteoporosis and that secretin is a specific protein for osteoporosis." (PMID 34754319, 2021). "Our findings demonstrate that QGY modulates the OPG/RANKL/RANK pathway by increasing secretin levels during treatment of primary type I osteoporosis." (PMID 34754319, 2021). "In our previous study, we found that secretin is a specific serum protein marker for patients with type I osteoporosis." (PMID 34754319, 2021). "Secretin, a hormone, is secreted by duodenal S cells and plays an important role in the pathological processes of digestive system diseases and osteoporosis." (PMID 34754319, 2021). "This experiment showed that our method of obtaining an osteoporosis model with secretin knockdown was successful, and the required time was much shorter compared with previous methods." (PMID 34754319, 2021). "Future controlled studies with larger sample sizes are required to determine the sensitivity and specificity of secretin in the diagnosis of osteoporosis." (PMID 27347465, 2016). "Therefore, it is important to elucidate the relationship among the QGY prescription, osteoporosis, secretin, and the OPG/RANKL/RANK pathway." (PMID 34754319, 2021). "We hypothesized that QGY regulates OPG/RANKL/RANK pathway by improving the level of secretin to treat the primary type I osteoporosis." (PMID 34754319, 2021). "Hence, we investigated the relationship between the OPG/RANKL/RANK pathway and secretin and further revealed the mechanism underlying the effect of QGY in the treatment of osteoporosis." (PMID 34754319, 2021). "Therefore, we used the AAV-mediated knockdown of the secretin gene to obtain an osteoporosis mouse model." (PMID 34754319, 2021). "Peripherally, sCT binds to calcitonin receptors on bone osteoclasts and the kidney (Marx, Woodard, & Aurbach 1972), and it has been used for the treatment of bone metabolic diseases that involve these receptors, for example, osteoporosis (Munoz‐Torres, Alonso, & Raya 2004)." (PMID 29405517, 2019). "However, the mechanism of action of secretin in osteoporosis remains unclear." (PMID 34754319, 2021). "Secretin levels are a serum marker of osteoporosis, but their effect on the OPG/RANKL/RANK pathway has not been reported." (PMID 34754319, 2021).
pancreatic diseases (6 papers, 2014 to 2023). "• Secretin increases the diagnostic capabilities of MRCP for evaluating pancreatic disorders." (PMID 27628744, 2016). "More recently, a protocol utilizing secretin-enhanced MRCP (S-MRCP) has been developed to diagnose various pancreatic disorders by increasing the secretion of pancreatic exocrine, inducing temporary pancreatic duct dilation." (PMID 37370939, 2023). "We have recently demonstrated that secretin-stimulated transabdominal ultrasonography (s-US) can detect reduced pancreatic secretion in various pancreatic diseases, and best accuracy for exocrine pancreatic failure was achieved for the method in CF patients." (PMID 29134356, 2018). "Pancreatic fluid flow in response to secretin stimulation in humans has been studied by MRI (s-MRI) for various pancreatic disorders." (PMID 29134356, 2018). "In this pictorial review, we present our experience with secretin-stimulated MRCP (SS-MRCP) findings observed in patients with diagnosed or suspected pancreatic disease, focussing on the main clinical applications of this MR technique." (PMID 27628744, 2016). "Thus the transient increase in the diameter of the pancreatic duct after the secretin stimulation improves the depiction of the ductal anatomy, which can be useful in patients in whom detailed evaluation of the pancreatic duct is most desired because of a suspicion of pancreatic disease." (PMID 24716074, 2014).
pancreatic exocrine insufficiency (5 papers, 2011 to 2024). "Other methods to measure pancreatic exocrine insufficiency include secretin-enhanced magnetic resonance cholangiopancreatography (S-MRCP) and the C13 mixed triglyceride breath test (C13-MTG)." (PMID 38398492, 2024). "Thus, at our institution secretin is only used in special cases when functional information on pancreatic juice secretion is needed (pancreatic insufficiency, papilla stenosis)." (PMID 31035952, 2019).
pancreatitis (5 papers, 2023 to 2026). Inflammation of the pancreas. "Prior studies in cats with and without cholangitis and pancreatitis and in a study in children showed that secretin enhances MRCP visualization of the pancreatic ducts due to its dilatory effect." (PMID 37570325, 2023). "In veterinary medicine, the potential of MRCP has been shown with and without secretin stimulation in healthy cats and cats with cholangitis and pancreatitis." (PMID 37570325, 2023).